CDC20 (cell division cycle 20)
Diseases named in the same sentence as CDC20 in open-access papers (continued):
Sharing a sentence is not in itself a finding about the gene and the disease.
osteosarcoma (continued). "Commercial carriers such as RNAiFectTM reagent (Qiagen), LipofectamineTM 2000 and OligofectamineTM(Invitrogen) were used to deliver CDC20, RAD51, and CHEK1 siRNA, respectively, and these studies were conducted in pancreatic, non-small-cell lung carcinoma (NSCLC), and osteosarcoma cell-lines." (PMID 25763370, 2015). "Furthermore, there is a strong inverse correlation of protein levels between BRD7 and Cdh1 or Cdc20, and lower BRD7 expression is an indicator for poor prognosis in patients with osteosarcoma." (PMID 24840027, 2014). "Moreover, the bioinformatics analysis showed that STIL may participate in the biological function of osteosarcoma by regulating CDK1, CCNB2, CDC20, CCNA2, BUB1, and AURKB." (PMID 33858425, 2021). "Furthermore, an inverse correlation was observed between the protein levels of BRD7 and Cdh1 or Cdc20 (p<0.001, χ2 tests), demonstrating that Cdh1 and Cdc20 may also negatively regulate BRD7 protein in osteosarcoma tissues." (PMID 24840027, 2014).
cervical cancer (11 papers, 2010 to 2025). A primary or metastatic malignant neoplasm involving the cervix. "In cervical cancer, Cdc20 overactivation causes premature chromosomal segregation and genomic instability." (PMID 40519296, 2025). "In this work we identified 6 genes (PRC1, CCNB2, SYCP2 CDKN3, NUSAP1, and CDC20) associated with invasive cervical cancer that could be used either as markers for diagnosis or as therapeutic targets." (PMID 23405241, 2013). "Of the top 10 ranked upregulated genes, 2 have not been previously reported as associated with cervical cancer (NUSAP1, and CDKN3), while the other 8 have been associated with cervical cancer either scantly (SYCP2, PRC1, CCNB2 and CDC20) or widely (MKI67, CDKN2A, CDC2, and PCNA)." (PMID 23405241, 2013). "Specifically, APS inhibits the cisplatin resistance pathway and regulates the cell cycle by suppressing the Wnt/β-catenin pathway via the PPARD/CDC20 axis; APS also influences autophagy and upregulates γH2AX expression, thereby enhancing cervical cancer sensitivity to radiotherapy." (PMID 41306775, 2025).
non-small cell lung carcinoma (11 papers, 2015 to 2024). A group of at least three distinct histological types of lung cancer, including non-small cell squamous cell carcinoma, adenocarcinoma, and large cell carcinoma. "In human non-small cell lung cancer, patients with tumor exhibiting high levels of CDC20 showed significantly shorter 5-year overall survival." (PMID 31106147, 2019). "Moreover, over-expression of gene CDC20 could predict poor prognosis in primary non-small cell lung cancer patients." (PMID 28587642, 2017). "In the context of non-small cell lung cancer (NSCLC), combining CDK inhibition with the resulting impact on CDC20 can be a strategic approach to limit the proliferation of cancer cells, potentially enhancing treatment effectiveness." (PMID 39457373, 2024).
oral squamous cell carcinoma (10 papers, 2012 to 2024). "Elevated CDC20 expression in oral squamous cell carcinoma cells causes premature anaphase due to disrupted APC activity, leading to genomic instability, including aneuploidy." (PMID 39795587, 2024). "Aberrant expression of CDC20 is associated with malignant progression and poor prognosis in various types of cancer, including gastric, urothelial bladder cancer, oral squamous cell carcinoma, and hormone-positive breast cancer." (PMID 36385010, 2022). "Overexpression of CDC20 in HeLa cells showed that a higher frequency of formation of multinuclear cells and in oral squamous cell carcinoma cells leads to an impairment in the spindle assembly checkpoint." (PMID 36834539, 2023).
pancreatic ductal adenocarcinoma (10 papers, 2012 to 2025). An infiltrating adenocarcinoma that arises from the epithelial cells of the pancreas. "CDC20 was detected to be upregulated in pancreatic ductal adenocarcinoma (PDAC), and overexpression of CDC20 was associated with poor differentiation and lower RFS of PDAC patients." (PMID 31106147, 2019). "One very recent study conducted in human pancreatic ductal adenocarcinoma cell lines revealed that inhibition of extracellular signal-regulated kinase (ERK) led to dephosphorylation of Cdc20 and concomitant loss of APC/C target proteins securin and cyclin B (CCNB1 and CCNB2)." (PMID 39412391, 2024). "It was reported that high expression of CDC20 (cell division cycle protein 20) is associated with poor survival in astrocytoma, cutaneous squamous cell carcinoma and pancreatic ductal adenocarcinoma." (PMID 33767726, 2021). "Increased CDC20 expression correlates with differentiation and progression of pancreatic duct adenocarcinoma." (PMID 36531013, 2022). "CDC20 overexpression may play a crucial role in the development and progression of pancreatic ductal adenocarcinoma, suggesting that CDC20 could serve as a prognostic marker and a potential therapeutic target." (PMID 39795587, 2024). "In this retrospective study, we determined whether aberrant CDC20 expression can be used as a biomarker in pancreatic ductal adenocarcinoma (PDAC) tumorigenesis and whether its expression reflects clinical progression." (PMID 22475564, 2012). "Cell division cycle 20 (CDC20) homolog is an anaphase-promoting complex activator that is essential for cell division, but whether its expression in pancreatic ductal adenocarcinoma (PDAC) is significant is unknown." (PMID 22475564, 2012).
breast tumor (8 papers, 2010 to 2023). "Pharmacological inhibition of ACK1 using its inhibitor, (R)-9b dampened CCNB1, CCNB2 and CDC20 expression, caused G2/M arrest, culminating in regression of palbociclib-resistant breast tumor growth." (PMID 37330596, 2023). "CP5V specifically degrades CDC20 by bridging CDC20 to the VHL/VBC complex for ubiquitination-mediated degradation, suppressing breast tumor progression." (PMID 35954396, 2022). "Another gene directly co-expressed with KPNA2 is the Cell division cycle 20 (CDC20), a late mitosis checkpoint mediator that predominantly occurs in hormone positive (ER +) breast tumours (58% (N = 870), METABRIC study)." (PMID 35948941, 2022). "The PR gene, PGR, and 3 other genes (GATA3, STC2 and GLI3) are increased in their expression, whereas the expression of 6 genes (AURKA, BUB1, CDC20, MKI67, HJURP, and CENPA) is decreased in PR-positive breast tumors." (PMID 22022496, 2011). "We further detect transcripts of ALDOA and several hub genes in breast tumors by RT-qPCR, and Pearson’s correlation analysis demonstrated a positive relationship of ALDOA with CCNB2 and CDC45, but not CDC20 and TK1, even a trend observed between them." (PMID 28191039, 2017).
renal cell carcinoma (8 papers, 2015 to 2026). "Next, based on clinical samples from renal cell carcinoma and matched normal tissues, the abundance of Cdc20 protein was dramatically increased in tumor tissues." (PMID 34527589, 2021). "Therefore, we examined the expression of CDC20 in renal cell carcinoma and clinicopathological characteristics and evaluated the prognostic value of CDC20 in renal cell carcinoma." (PMID 35800227, 2022). "In summary, the results suggested that the expression of CDC20 could be used as an independent indicator of the prognosis of renal cell carcinoma, and the increased expression of CDC20 in KIRC indicated a poor prognosis." (PMID 35800227, 2022). "In renal cell carcinoma (RCC), we identified conserved metabolichighUBE2C+ cancer cells linked to poor outcomes, metabolic reprogramming and low differentiation, and PLK1+ NK cells, plasma cells, and CDC20+ macrophages associated with advanced stages and unfavorable prognosis." (PMID 42196432, 2026).
COVID-19 (7 papers, 2021 to 2025). A disease caused by infection with severe acute respiratory syndrome coronavirus 2. "The GSE167028 and GSE150392 datasets were subjected to a recent bioinformatic analysis, which unveiled six critical genes (CDK1, KIF20A, PBK, KIF2C, CDC20, and UBE2C) associated with COVID-19 myocarditis." (PMID 40230577, 2025). "An IPIN analysis in COVID-19-induced thrombocytopenia also reported that CDC20 was highly expressed in COVID-19 with thrombocytopenia." (PMID 35625619, 2022). "In the study of tissue regeneration after acute injury, we analyzed the database of ALF and COVID-19 by bioinformatics method and found common hub genes, including CDC20, CENPF, KIF4, KIF11, NUSAP1, TPX2, and PTTG1, which were related to mitosis and cell cycle regulation." (PMID 36911196, 2023). "CDC20 and KIF11 were listed as hub genes for COVID-19 treatment and novel therapeutic targets against SARS-CoV-2 infections." (PMID 36911196, 2023). "As for the remaining genes, CDC20 and KIF2C were identified as target genes of COVID-19 by bioinformatics means and machine learning." (PMID 35749386, 2022). "Eventually, 6 genes (CDK1, KIF20A, PBK, KIF2C, CDC20, UBE2C) were identified by CytoHubba plug-in of Cytoscape as critical genes of COVID-19 Myocarditis for future study." (PMID 35749386, 2022). "Based on 5 algorithms of the CytoHubba plug-in, six genes (CDK1, KIF20A, PBK, KIF2C, CDC20, UBE2C) were confirmed as critical genes related to COVID-19 Myocarditis." (PMID 35749386, 2022). "The therapeutic effect of an inhibitor for a hub gene CDC20 on acute liver failure was verified in the ALF mice model, which may provide a new method for treating ALF and COVID-19." (PMID 36911196, 2023). "The hub genes identified in this paper and their corresponding targets, such as CDC20 inhibitor-Apcin, may be a new possible approach for ALF and COVID-19 treatment." (PMID 36911196, 2023). "It is worth highlighting that critical genes (CDK1, KIF20A, PBK, KIF2C, CDC20, UBE2C) may be potential biomarkers and treatment targets of COVID-19 Myocarditis for future study." (PMID 35749386, 2022). "In addition, CAV1, CDC20, and KIF20A were also identified as hub genes in COVID-19 by other researchers." (PMID 35957855, 2022). "Based on topological algorithms (i.e., degree), in this study, CDK1, KIF20A, PBK, KIF2C, CDC20, and UBE2C were identified as critical genes that may be potential biomarkers for COVID-19 Myocarditis." (PMID 35749386, 2022).
Infertility (7 papers, 2010 to 2023). "CDC20 has also been shown to play an important role in meiosis occurring in the oocyte, where detected mutations within this gene lead to infertility in women." (PMID 37550786, 2023). "We identified four novel mutations and one previously reported mutation in CDC20 in four infertile individuals from three independent families." (PMID 33898437, 2021). "In light of the important role of CDC20, we screened for novel CDC20 mutations in a new cohort of infertile female patients with abnormalities in the processes of oocyte maturation, fertilization, and early embryonic development." (PMID 33898437, 2021). "They showed that female mice with low amounts of Cdc20 almost exclusively produced aneuploidy embryos, resulting in failure to thrive and death early in development, and suggested the possibility that Cdc20 insufficiency may be a cause of infertility." (PMID 28806906, 2017). "Notably, in mice it has been reported that CDC20 may be required for anaphase onset during the first meiosis, thus raising also the possibility that CDC20 insufficiency may be a cause of infertility in otherwise healthy females." (PMID 25470487, 2014). "Inactive CDC20 can cause infertility in male mice without hurting overall health and viability." (PMID 29245942, 2017).
multiple myeloma (7 papers, 2016 to 2022). "Recently, we showed that Cdc20 is significantly higher expressed in high-risk myeloma patients and this elevated Cdc20 correlates with a poor prognosis." (PMID 29163849, 2017). "Moreover, gene expression analysis of newly diagnosed myeloma patients revealed a higher Cdc20 expression in high-risk patients, correlating with poor prognosis." (PMID 29163849, 2017). "Expression in myeloma cells is highly correlated to CDC20 and CCNB1/2 expression, and leads to increased myeloma proliferation." (PMID 29100463, 2017). "The aim of this study is to elucidate the importance and therapeutic potential of APC/C and its co-activator Cdc20 in multiple myeloma (MM)." (PMID 26716651, 2016). "Preclinical findings showed that selective CDC20 and APC/CCDC20/APC/CCDH1 inhibitors, namely Apcin and proTAME, are effective against lymphoma and multiple myeloma cells, resulting in mitotic arrest and apoptosis and synergizing with clinically-relevant drugs." (PMID 35490245, 2022). "APC/C-related and phosphoinositide pathway genes, such as CDC20, CDH11, PTEN and others, may also be involved in CIN in myeloma." (PMID 29100463, 2017).
triple-negative breast carcinoma (7 papers, 2019 to 2025). An invasive breast carcinoma which is negative for expression of estrogen receptor (ER), progesterone receptor (PR), and human epidermal growth factor receptor 2 (HER2). "For example, high CDC20 expression increases tumor cell growth and migration in triple-negative breast cancer." (PMID 40092489, 2025).
cardiac hypertrophy (6 papers, 2019 to 2025). "Our previous study demonstrated that CDC20 overexpression exacerbated transverse aortic constriction-induced cardiac hypertrophy and cardiomyocyte enlargement in mice." (PMID 40045239, 2025). "CDC20 (anaphase-promoting complex activator) upregulation has been demonstrated in cases of cardiac hypertrophy." (PMID 36012897, 2022). "During recent years, several E3 enzymes, such as F-box protein atrogin-1, muscle ring finger-1, TRAF6, and CDC20 have been reported to play roles in the development of cardiac hypertrophy through different mechanisms." (PMID 33585485, 2021). "In addition, CDC20 can contribute to cardiac hypertrophy by promoting LC3 degradation and inhibiting autophagy." (PMID 35126643, 2022). "CD20 downregulation has been associated with reduction of NOX4 and ROS levels and further cardiac hypertrophy inhibition, whereas ectopic CDC20 expression enhanced cardiac hypertrophy via direct degradation of the autophagy regulator LC3 and further autophagy impairment." (PMID 36012897, 2022). "CDC20 can contribute to cardiac hypertrophy by promoting LC3 degradation and inhibiting autophagy." (PMID 31737652, 2019).
cutaneous squamous cell carcinoma (6 papers, 2019 to 2024). "The deficiency of CDC20 has been demonstrated to decrease the percentage of G0/G1 phase and increase the percentage of G2/M phase in cutaneous squamous cell carcinoma cells." (PMID 38419324, 2024). "In cutaneous squamous cell carcinoma, CDC20 promotes cell proliferation and migration through the Wnt/β-catenin signaling pathway." (PMID 31737652, 2019). "CDC20 can promote the proliferation of cutaneous squamous cell carcinoma." (PMID 33035258, 2020).
leukemia (6 papers, 2020 to 2025). A malignant (clonal) hematologic disorder, involving hematopoietic stem cells and characterized by the presence of primitive or atypical myeloid or lymphoid cells in the bone marrow and the blood. "CDC20 was downregulated in the ZBAexo group, high levels of CDC20 have been observed in various leukemia subtypes and are associated with poor prognosis." (PMID 41424711, 2025). "BI-D1870, the inhibitor of RSK, potentiated anti-leukemia activity of vincristine, which prevent the association of activator CDC20 with APC/C and impeded mitosis exit." (PMID 34051812, 2021). "MLL fusion proteins are resistant to ubiquitin‐proteasome‐mediated degradation due to the diminished interactions with E3 ligases Skp2 and Cdc20,37 leading to the stabilization and onset for MLL‐rearranged leukaemia." (PMID 33599085, 2021). "CDC20 fails to interact with MLL fusions in human MLL leukemia cells, which continue to promote the progression of the cell cycle." (PMID 32219041, 2020).
astrocytoma (5 papers, 2021 to 2025). "The results revealed higher CDC20 expression in the GBM tissues than in the normal or astrocytoma tissues." (PMID 40439120, 2025). "Tissue array analysis revealed higher expression of CDC20 in GBM tissues than in normal or astrocytoma tissues." (PMID 40439120, 2025). "In this study, to evaluate the association between CDC20 expression and brain cancer grade, we conducted a brain cancer TMA of tissues with different grades of brain cancer, including normal tissues, tissues with astrocytoma and tissues with GBM." (PMID 40439120, 2025).
clear cell renal cell carcinoma (5 papers, 2021 to 2025). "Consistent with the literature, CDC20 was coexpressed with UBE2C in human clear cell renal cell carcinoma." (PMID 35804892, 2022). "This article analyzes the relationship between cell division cycle (CDC20) molecules and oncology outcomes in patients with renal clear cell carcinoma (KIRC)." (PMID 35800227, 2022). "A recent study identified that nine key genes including CDC20 were potential diagnosis genes in clear cell renal cell carcinoma." (PMID 34513754, 2021). "CDC20 could be used as an independent prognostic factor for clear cell renal cell carcinoma and was closely related to body immunity." (PMID 35800227, 2022). "One study by Yongwen (2019) identified 9 key genes in clear cell renal cell carcinoma, which including UBE2C and CDC20." (PMID 36385010, 2022).
diffuse large B-cell lymphoma (4 papers, 2020 to 2025). "CDC20 and CDC25C are highly expressed in diffuse large B cell lymphoma, suggesting that these genes may also influence B cell growth and development." (PMID 40565588, 2025).
endometrial cancer (4 papers, 2019 to 2022). Primary or metastatic malignant neoplasm involving the endometrium (mucous membrane that lines the endometrial cavity). "In summary, ZXF1 regulates P21 expression in endometrial cancer through two mechanisms: by regulating P21 protein expression through the miR‐378a‐3p/PCDHA3 axis and by directly binding to P21 to prevent its CDC20‐mediated ubiquitin degradation." (PMID 33751805, 2022). "The CDC20 (50.25 ± 1.74 vs 23.67 ± 3.43, p < 0.01) and CCNA2 (46.65 ± 1.44 vs 24.67 ± 2.43, p < 0.01) shows significantly higher expression in endometrial cancer than cancer adjacent tissue." (PMID 31289358, 2019). "We selected the two hub genes (CDC20 and CCNA2) that rarely been studied in endometrial cancer to evaluate gene expression values using IHC." (PMID 31289358, 2019). "The gene function was evaluated by cell growth curve after knockdown CDC20 and CCNA2 of endometrial cancer cell line." (PMID 31289358, 2019).
head and neck cancer (4 papers, 2020 to 2023). A primary or metastatic malignant neoplasm affecting the head and neck. "While a possible role for CDC20 in treatment resistance has previously been explored in head and neck cancers, our results are the first to suggest a direct and causal link between CDC20 and radio- and chemoresistance in GSCs." (PMID 35737702, 2022).
lymphoma (4 papers, 2019 to 2023). A malignant (clonal) proliferation of B- lymphocytes or T- lymphocytes which involves the lymph nodes, bone marrow and/or extranodal sites. "Together, these data suggest that increased Cdc20 expression is associated with high-grade lymphoma and Cdc20 thus represents an interesting therapeutic target." (PMID 31089208, 2019). "A significant higher amount of Cdc20-positive lymphoma cells was counted in the patients with a poor prognosis compared with the patients with a good prognosis (p = 0.0042)." (PMID 31089208, 2019). "The percentage Cdc20-positive lymphoma cells was counted and plotted against the patient’s prognosis according to their R-IPI." (PMID 31089208, 2019).